U2 (U2 spliceosomal RNA )
Synonyms: LOC124904139
Gene: Small nuclear RNA gene on chromosome 17 (43,266,633 to 43,266,823, reverse strand). Ensembl gene ENSG00000276596.
Gene Ontology:
Molecular function: pre-mRNA branch point binding
Biological process: mRNA branch site recognition
Cellular component: U2 snRNP
Homologues: Orthologues: chimpanzee U2 (100% identical), macaque U2 (100% identical), dog U2 (99% identical), pig U2 (48% identical), rat LOC120094029 (36% identical). Paralogues in human: U2 (100% identical), RNU2-2 (96% identical), U2 (95% identical), RNU2-3P (93% identical), RNU2-4P (93% identical), RNU2-17P (90% identical), RNU2-6P (90% identical), RNU2-48P (89% identical), RNU2-52P (89% identical), RNU2-59P (89% identical), RNU2-25P (87% identical), RNU2-26P (87% identical), and 68 more.